IL10 (interleukin 10)
Diseases named in the same sentence as IL10 in open-access papers (continued):
Sharing a sentence is not in itself a finding about the gene and the disease.
Arthritis (continued). "On the other hand, a lack of IL‐10 might result in increased immune cell activation and long‐lasting inflammatory reactions, aggravating the course of arthritis." (PMID 39479687, 2024). "The anti-inflammatory cytokine IL-10 was significantly decreased (53% decrease, P = < 0.001), while the inflammatory markers IL-17 (2.8-fold increase, P = < 0.001) and CRP (9.38 folds increase, P = < 0.001) increased in the untreated arthritis group versus the control group." (PMID 37389660, 2023). "Similarly, chimeric mice lacking IL-10 producing B cells developed an exacerbated collagen-induced arthritis and demonstrate an increased amount of proinflammatory Th 1 as well as Th 17 cells." (PMID 35743787, 2022). "Furthermore, butyrate supplementation failed to suppress disease in mixed bone marrow chimeric mice lacking IL-10-producing B cells, pinpointing the requirement of Bregs in the butyrate-mediated suppression of arthritis." (PMID 32213346, 2020). "Conversely, anti-inflammatory cytokines (e.g., IL-10, TGF-β, and IL-13) may dampen arthritis." (PMID 28057980, 2016). "Here, we demonstrated that a single treatment with FBP markedly attenuated arthritis, assessed by reduction of articular hyperalgesia, joint swelling, neutrophil infiltration and production of inflammatory cytokines, TNF and IL-6, while enhancing IL-10 production in two mouse models of arthritis." (PMID 26478088, 2015). "The high IL-10 production could be an important contribution to the anti-inflammatory effects of Lip-PLP as IL-10 and glucocorticoids can work synergistically on the suppression of inflammation during experimental arthritis." (PMID 23468840, 2013). "However, in our study, the protective effect of α-GalCer against arthritis was not due to the induction of antigen-specific IL-10 producing cells." (PMID 23251456, 2012). "So, despite the induction of an obvious HSP70-specific response, the protective effects of HSP70 immunization on the PG-specific B and T cell response were shown to be IL-10 dependent, consequently leading to development of severe arthritis in the absence of IL-10." (PMID 19142233, 2009). "However, the adoptive transfer of IL-10−/− B cells does not prevent arthritis in this model system." (PMID 26236565, 2015). "This research described the antioxidant (SOD3, CAT, GPX, ATOX1 and COX18) and immunological (IL-1α, IL-1β, IL-6, IL-10, TNFα, NCF4, NFKB, TMED, FCAMR and iNOS) genes in rams that had arthritis and those that did not." (PMID 40005882, 2025). "The levels of IL-2, IL-12p40, IL-12p70, and IL-15, as well as those of IL-10 and IL-13, did not increase in the setting of CFA-induced arthritis." (PMID 36293292, 2022). "In CIA mice, alantolactone at 50 mg/kg attenuated RA symptoms, including high arthritis scores, infiltrating inflammatory cells, synovial hyperplasia, bone erosion and levels of the proinflammatory cytokines TNF-α, IL-6 and IL-17A, but not IL-10 in paw tissues." (PMID 33556301, 2021).
atherosclerosis (312 papers, 2007 to 2026). A disease characterized by the build-up of fatty material and calcium deposition in the arterial wall resulting in partial or complete occlusion of the arterial lumen. "IL-10 has been implicated in a variety of inflammatory processes, including modulation of atherosclerosis, endothelial dysfunction, and immune responses to vascular injury." (PMID 40429759, 2025). "Knockout of IKK2 in macrophages in a mouse model of atherosclerosis revealed a reduction of TNFα expression and strong loss of IL-10 in macrophages when challenged by LPS38." (PMID 40461478, 2025). "In another study, PDCD4-deficient mice with an induced increase in IL-10 expression attenuated the progression of atherosclerosis." (PMID 36831189, 2023). "Transgenic mice over-expressing IL-10 show reduced atherosclerotic plaques, while IL-10 deficient mice have significantly worse atherosclerosis compared to WT controls." (PMID 36994095, 2023). "IL10 is expressed in atherosclerotic plaques, and its encoded protein, IL-10, is an antiinflammatory cytokine that inhibits many cellular processes that advance human atherosclerosis." (PMID 37498674, 2023). "Treg cells have an anti-atherosclerotic role, their presence being increased along with IL-10 in those with a reduced risk for atherosclerosis." (PMID 37600028, 2023). "IL-10 deficiency is reported to increase atherosclerotic plaque size and promote atherosclerosis development." (PMID 35303193, 2022). "Future studies will be needed to clarify the detailed molecular mechanisms by which IL-10 deficiency impairs the LRP1-mediated RCT pathway to promote atherosclerosis." (PMID 36110841, 2022). "In an atherosclerosis setting, peritoneal macrophages from miR-155-deficient mice were more pro-inflammatory and produced less IL-10 following LPS stimulation." (PMID 35020867, 2022). "Depletion of Treg cells in mice aggravates atherosclerosis and Tregs express IL-10 and transforming growth factor (TGF)-β, both associated with anti-atherosclerotic effects in atherosclerosis." (PMID 35087886, 2021). "Meanwhile, overexpression of IL-10 or IL-10 deficiency demonstrated remarkable amelioration or exacerbation of the development of atherosclerosis." (PMID 34471467, 2021). "Consistently, supplementation of IDO-deficient mice with physiological levels of Kna limited IL-10 expression and promoted atherosclerosis." (PMID 34576067, 2021). "The development of atherosclerosis was attenuated by in vivo induction of Tr1 cells in atherosclerosis-prone mice, which was associated with increased production of IL-10." (PMID 34945203, 2021). "Together, our results indicate that hematopoietic SLC37A2 deletion worsens atherosclerosis, inversely associated with plasma IL-10 levels." (PMID 34957260, 2021). "Recently, growing evidence has indicated the relationship between IL-10 and cardiovascular diseases (CVD), particularly atherosclerosis, and IL-10 is believed to be a potential predictor for CVD risk." (PMID 33456490, 2020). "A study found that increased FOXP3-TSDR methylation levels were significantly associated with the severity of atherosclerosis and the changes in IL-10 concentration." (PMID 32582189, 2020). "Further to this, IDO deficiency dysregulates cytokine IL-10 release and promotes early-stage atherosclerosis." (PMID 33117340, 2020). "IL-10 deficiency elevated atherosclerotic plaque size and promoted the development of atherosclerosis, and the human IL-10 gene transfer decreased atherosclerosis and atherosclerotic plaque instability." (PMID 33029103, 2020). "Antiatherogenic inflammatory cytokine IL-10 deficiency elevated atherosclerotic plaque size and promoted the development of atherosclerosis." (PMID 33029103, 2020).
atherosclerosis (continued). "T-bet deficiency slows atherosclerosis development and increases production of the atheroprotective Th2 cytokines IL-4, IL-5, and IL-10, and IgM antibodies." (PMID 31653058, 2019). "IL-10, on the other hand, is a predominantly anti-inflammatory cytokine and would be expected to be associated with reduced atherosclerosis by suppressing macrophage activation and inhibiting several proinflammatory cytokines, chemokines, and growth factors." (PMID 29132841, 2017). "Low levels of expression of IL-10 are associated with atherosclerosis and cardiac and vascular dysfunction in mouse models, and in humans, reduced levels of IL-10 are associated with carotid atherosclerosis and coronary disease." (PMID 25948070, 2015). "IL-10 is an anti-inflammatory cytokine, which down-regulates many inflammatory pathways that are associated with atherosclerosis." (PMID 24485322, 2014). "IL-10 has been shown to be associated with protective functions in human atherosclerosis, consistent with mouse data." (PMID 23248624, 2012). "In these ApoE−/− mice, the deletion of CCR5 protects from diet-induced atherosclerosis, associated with a more stable plaque phenotype, reduced mononuclear cell infiltration, Th1-type immune responses, and increased interleukin-10 expression." (PMID 21188276, 2010). "Some studies suggest that IL-10 may have a preventive effect against the development and progression of atherosclerosis, as higher serum levels of IL-10 are associated with lower carotid intima-media thickness (CIMT) values." (PMID 39273602, 2024). "Pro-inflammatory cytokines such as IL-1β, IL-6 and TNF-α and anti-inflammatory cytokines such as IL-4 and IL-10 provide further insights into the mediators of cellular and systemic responses and have been linked to causal pathways related to atherosclerosis and thrombosis." (PMID 39767790, 2024). "Similarly, IL-10-deficient mice were found to have a substantially increased susceptibility to atherosclerosis compared to normal mice, as evidenced by increased T cell infiltration, high IFN-γ expression, and reduced collagen content." (PMID 39399488, 2024). "Another interleukin inversely associated with atherosclerosis, IL-10, was also assessed." (PMID 36904211, 2023). "Raised inflammatory cytokines like TNF-α and deficient IL-10 lead to severe atherosclerosis." (PMID 36763189, 2023). "Furthermore, B1 B cell-derived IL-10 production has been associated with attenuated responses to infections with Leishmania and atherosclerosis and seems to enhance B1 B cell expansion via induction of proliferation." (PMID 35572585, 2022). "Upon high cholesterol/high fat diet feeding, IL-10-deficient hamsters exhibited abnormal distribution of triglyceride and cholesterol in lipoprotein particles, impaired lipid transport in macrophages and aggravated atherosclerosis." (PMID 36110841, 2022). "Atherosclerosis, a chronic inflammatory disease of the arterial wall, has been reported to be associated with various inflammatory cytokines, such as IL-10 and TGF-β, which are associated with Tregs as well as IFN-γ, TNF-α, and IL-17, which are associated with Th1 and Th17 cells." (PMID 36405994, 2022).
atherosclerosis (continued). "The anti-inflammatory interleukin-10 (IL-10), which is associated with reduced apoptosis of cells of the lipid core and thereby with the reduced risk of plaque rupture, has been related to reduced risk of developing atherosclerosis." (PMID 36233355, 2022). "We then assessed whether there is an association between plasma lipids vs. atherosclerosis or between plasma IL-10 vs. atherosclerosis in diet-fed mice by performing linear regression analysis." (PMID 34957260, 2021). "Accordingly, IL-10 deficiency promotes atherosclerosis in mice." (PMID 33669769, 2021). "Indeed, double deficiency IDO/IL-10 led to exaggerated immune responses and these mice developed severe spontaneous colitis and accelerated atherosclerosis." (PMID 34576067, 2021). "In contrast, IL-10 has well-described anti-atherogenic properties and is often associated with regulatory T cells, which can suppress activation and proliferation of immune cells during atherosclerosis, including IFNγ-producing CD4+ T cells." (PMID 34790707, 2021). "Animal studies showed that IL-10-deficient mice developed significantly more atherosclerosis, with elevated T cell accumulation, IFNγ expression, and reduced collagen content in the lesion, concordant with its role as a potent inhibitor of inflammatory responses." (PMID 33562334, 2021). "In mouse model, IL-10 deletion exaggerates inflammatory cytokines accumulation and is associated with a variety of pathogenic outcomes including endotoxemia, intestinal inflammation and atherosclerosis." (PMID 26808574, 2016). "We also studied the FcγR and IL10 genotypes as they have been linked to atherosclerosis." (PMID 25948070, 2015). "Although the sequence of chemical base pairs and most of the single nucleotide polymorphisms (SNP) of the IL-10 gene have been identified, their role in the regulation of IL-10 production and also their influence on atherosclerosis remains largely unknown." (PMID 24040186, 2013). "In support of this explanation, higher plasma concentrations of IL-10 have been detected in plasma of patients with stable, versus unstable coronary syndromes and, experimentally, IL-10 deficiency results in increased atherosclerosis in apolipoprotein E-deficient mice." (PMID 17328808, 2007). "Therefore, upon CLEC9A deletion, the increased expression of IL10/IL-10 in the BM and CD8α+ DCs seem to be the main cause of reduced recruitment or the activation of macrophages in plaque sites, as well as the alleviation of atherosclerosis." (PMID 39528464, 2024). "For instance, in a model of early atherosclerosis, low-density lipoprotein receptor deficient mice transplanted with miR-155-deficient bone marrow had increased atherosclerotic plaques, elevated levels of pro-inflammatory monocytes, and decreased interleukin (IL)-10 production." (PMID 36142173, 2022). "Furthermore, both IL-10 (Interleukin 10) and IL-12 (Interleukin 12) have important roles in the regulation of the innate immune system and have been associated with the inflammatory state of atherosclerosis observed in PAD." (PMID 35298547, 2022). "Interestingly, in the presence of angiotensin II, adoptive transfer of B cells into B cell-deficient Apoe−/−Baffr−/− mice prevented the progression of atherosclerosis and was associated with a significant increase in IL-10 producing regulatory CD1highCD5+ B cells." (PMID 33572939, 2021). "Similarly, some studies have reported a long-term increase in serum IL-10 levels in patients with unstable CAD or myocardial infarction compared to levels in healthy subjects or those with stable CAD, and IL-10 levels are higher in high-risk patients with atherosclerosis." (PMID 34660716, 2021).
atherosclerosis (continued). "The possible mechanism underlying the regulatory effect of rSj-Cys on reducing atherosclerosis and atherosclerotic renal damage is that rSj-Cys stimulates regulatory T cell and M2 macrophage polarization that produce regulatory cytokines, such as interleukin 10 and transforming growth factor β." (PMID 34901005, 2021). "Furthermore, aside from inducing IFN-γ, IL-18 can also induce expression of TNF-α and synthesis of IL-10, cytokines that can inhibit the inflammatory process, leading to the instability of atherosclerosis plaques and formation of thromboses, a main risk factor for stroke." (PMID 31525735, 2019). "Adoptive transfer of Apoe−/−/Baffr−/− mice with Il-10−/− B cells did not alter BAFF levels but resulted in a significant reduction of IL-10 production in splenocytes, splenic B cells and CD1dhiCD5+ B cells (data not shown), and was associated with a significant acceleration of atherosclerosis." (PMID 28646220, 2017). "Also in genetically CCR5 deficient mice with diet induced atherosclerosis, reduced lesion size, increased IL-10 and decreased TNF-α production by CD4+ and CD8+ T cells, and reduced macrophage accumulation in plaques and lowered circulating IL-6 levels was seen." (PMID 22348061, 2012). "This study aimed to investigate the feasibility and effectiveness of an approach designed to overexpress IL‐10 in macrophages and subsequently introduce these genetically modified cells into an atherosclerosis mouse model." (PMID 39801756, 2025). "Macrophages synthesize putrescine from AC-derived arginine and ornithine to sustain efferocytosis, MerTK expression, IL-10 production, inflammation resolution, and, ultimately, atherosclerosis regression." (PMID 40833492, 2025). "For example, macrophage cells were transfected by IRES‐IL‐10 plasmids to produce IL‐10 mRNA which controlled atherosclerosis treatment." (PMID 41476648, 2025). "We have recently shown “that macrophages derived from LPS stimulated monocytes in individuals with subclinical atherosclerosis exhibited increased secretion of IL6, IL10 and CCL2, which was associated with intima-media thickness”." (PMID 38441018, 2025). "Vaccine-based immunotherapy against atherosclerosis-relevant antigens, such as ApoB-derived peptides, has shown promise in preclinical models by expanding FoxP3+ regulatory T cells and IL-10-producing B cells." (PMID 40833492, 2025). "Studies have sought to address these limitations by delivering encapsulated IL‐10 within nanoparticles for the treatment of atherosclerosis." (PMID 39801756, 2025). "In this study, we aimed to investigate the effectiveness of an approach designed to overexpress IL‐10 in macrophages and subsequently introduce these genetically modified cells into ApoE−/− mice to promote atherosclerosis regression." (PMID 39801756, 2025). "As a result, EVs loading IRSE‐IL‐10 mRNA were specifically delivered to atherosclerosis plaque, and IL‐10 protein expressing further alleviated atherosclerosis." (PMID 41476648, 2025). "Like IL-27 and IL-35, IL-10 signaling affects various immune cell types involvedin the pathogenesis of atherosclerosis." (PMID 40160593, 2025). "The delivery of IL-10 via engineered exosomes, which decreases atherosclerosis in ApoE (−/−) mice, is an encouraging strategy." (PMID 38558788, 2024). "Vitamin D decreases inflammatory markers (C-reactive protein, Interleukin 10) and oxidative stress markers (free radicals, nitric oxide), thus influencing atherosclerosis." (PMID 38592202, 2024). "Conversely, in the context of atherosclerosis, IL-10 alleviates inflammation in the atheroma plaque." (PMID 39702436, 2024). "Disruption of the CCL1-CCR8 axis facilitates atherosclerosis by inhibiting IL-10 production and Tregs recruitment and function." (PMID 39399488, 2024).